IL1B (interleukin 1 beta)
Diseases named in the same sentence as IL1B in open-access papers (continued):
Sharing a sentence is not in itself a finding about the gene and the disease.
parasitemia (64 papers, 2005 to 2026). "IL-1β rs1143634 is notably associated with patient parasitemia, whereas IL-18 rs5744256 appears to play a protective role against anemia development." (PMID 39548522, 2024). "Parasite density was the principal predictor of the cytokine levels, as parasitemia positively associated with IL‐10, GM‐CSF, IL‐6, IL‐1β, IFN‐ɣ, and TNF‐α, but negatively associated with IL‐3 and TGF‐β." (PMID 39240033, 2024). "In the past, the activity of inflammasomes and the associated production of especially IL-1β has been correlated with the host protection against parasitic infections, for instance in the case of T. cruzi or T. gondii." (PMID 26114647, 2015). "IL-1β has been associated with the control of parasitic infections possibly including various Leishmania species." (PMID 26114647, 2015). "It is currently unknown whether associations between IL1B 3953C>T and cerebral malaria or parasitemia in African populations result from a LD with other functional polymorphisms in this chromosomal region." (PMID 16098232, 2005). "In the present study, the correlation between the Th2-type cytokine IL-5 and the Th1-type cytokines IFN-γ and IL-1β in AE patients may be associated with the enhanced immunological response induced by parasite infection, which indicates that an inflammatory reaction is induced in AE patients." (PMID 32539714, 2020). "It is known that TNF-α promotes the induction of IL-6 and IL-1β; high levels of these cytokines can cause systemic inflammation and the combination of oxidative stress and inflammatory activation is commonly associated to several degenerative processes triggered by parasitosis." (PMID 28177049, 2017). "Upon A-2S stimulation, infγ was significantly upregulated only at week 2 of infection in immunosuppressed fish and il-1β at the onset of parasitemia (week 4) in SPF and S. molnari-infected fish." (PMID 40391212, 2025). "In parasitic diseases such as leishmaniasis, there is a complex interaction between different Leishmania species and the host immune system, mediated by cytokines such as IL-1β and IL-10, which determines the clinical outcomes of the disease." (PMID 41200163, 2025). "IL-1β is a key proinflammatory cytokine involved in host defense against parasitic infections, primarily by recruiting neutrophils and macrophages, enhancing phagocytosis, and regulating immune responses." (PMID 40109888, 2025). "In the present study, the expression of cytokines such as IFN-γ, IL-10, IL-12, CYP-1α, and IL-1β significantly increased in fish infected with Clinostomum and Euclinostomum, suggesting an immune response aimed at combating the parasitic infection." (PMID 41152306, 2025). "In acute parasitic infections, IL-1β typically acts as an early immune responder, triggering inflammasome activation and amplifying cytokine signaling." (PMID 40109888, 2025). "In chronic parasitic infections, sustained IL-1β secretion can contribute to excessive inflammation and tissue damage." (PMID 40109888, 2025). "During parasitic infection, significant upregulation of IL-1β, TNF-α, and Ig gene were observed in C. punctata liver and kidney samples (except TNF-α was downregulated in kidney)." (PMID 38476164, 2024). "Children with high parasite density (>10,000 parasites/μL) had higher plasma levels of TNF‐α (p < .001), IFN‐ɣ (p < .001), IL‐1β (p < .001), IL‐6 (p < .001), GM‐CSF (p < .001), and IL‐10 (p < .001) than those with low parasitemia." (PMID 39240033, 2024). "In mothers of babies congenitally infected with T. cruzi, parasitemia was positively correlated only with IL-15 and inversely correlated with IL-1β." (PMID 38133693, 2023). "Il1β transcript abundance positively correlated with parasitemia in the E6.5 infection group and multivariate modeling showed that infection at E8.5 increased placental transcription of this factor." (PMID 35312688, 2022).
parasitemia (continued). "During the acute stage (60 days postinfection (dpi)) Il-1r−/− mice reached greater parasitemia than WT mice, confirming that IL-1β signaling during the acute stage contributes to reducing parasite burden." (PMID 36341442, 2022). "In the E8.5 infection group, transcript abundance of all the inflammatory genes targeted, except for Il1β, was significantly elevated in placentae collected on E16.5, but no correlative relationships with parasitemia at sacrifice or parasitemia AUC were found." (PMID 35312688, 2022). "In baso (+) mice at day 3 p.i., parasitemia was directly and negatively correlated with plasma IL-1β and IL-3, whereas MIP-1β was directly and strongly positively correlated with gametocytemia." (PMID 35970557, 2022). "TNFα and IL-1β are proinflammatory cytokines crucial for immune responses, especially important for host defense from bacterial, viral, and parasitic infections." (PMID 33776573, 2021). "In participants with non-severe vivax malaria, our analysis revealed that only MDP levels of IL-1β and IL-4 were positively correlated with parasitemia." (PMID 34727121, 2021). "In order to determine if the increase in the induction of IL-1β release in Δmag1 parasite infection is dependent on GRA15, we produced a T. gondii strain with a double deletion, Δmag1 Δgra15." (PMID 34006649, 2021). "During parasitemia (day 9) monocytes produced less IL-6 and IL-1β compared to baseline in response to all tested stimuli." (PMID 33324683, 2020). "Our data support a protective role of IL17A AA, IL18 AA, and IL1B TC genotypes against development/progression of cardiomyopathy and a modulatory effect of the IL6 CG genotype on the risk of parasitemia in Chagas disease." (PMID 33193300, 2020). "Pyrogenic cytokines such as IL-1β, TNFα, IL-6 and IFNγ were significantly increased in plasma at peak parasitemia when the animals were presenting with clinical illness." (PMID 31536608, 2019). "IgM is involved in the fight against parasitic infection while cytokines, such as IL-6, IL-1β and TNF-α, had an impact on infection processes." (PMID 31882981, 2019). "Since IL-1R is required for IL-1β produced by inflammasome activation, we next infected 6–8 weeks-old WT and Il1r1−/− mice with a lethal dose (0.5 × 106 iRBCs) of YM, and monitored parasitemia and disease progression." (PMID 30470758, 2018). "Together, these results show that eATP induced the production of key molecules for the control of intracellular parasite infection—ROS and IL-1β—even in the presence of T. gondii and its evasion mechanisms." (PMID 29075257, 2017). "Parasitemia was significantly correlated with the following cytokines, in order of strength of association: IL-10, IL-12, TNF-α, IFN-γ, IL-1β, IL-6, IL-5, IL-2, IL-4, and IL-7." (PMID 27418744, 2016). "As expected the results were in accordance with the data acquired using parasite infections and culture supernatant treatment of cells, with both secretome and exosomes inhibiting IL-1β production induced by either HZ or MSU." (PMID 26114647, 2015). "Our study demonstrated that infection with the nahG-transfectant induced upregulation of proinflammatory cytokines including IFN-γ, IL-1β, IL-2, and IL-12, while parasitemia and hematocrit were almost uniform at the same time point." (PMID 26466097, 2015). "Firstly, during the innate response, T. gondii infection triggers the production of inflammatory cytokines IL-1β, IFNα/β, IL-6, IL-12, IL-15, and IL-18, driving NK cell production of IFNγ, resulting in early control of parasite infection by targeting intracellular parasites." (PMID 37018796, 2023). "On the day before preterm delivery, E6.5 infected mice did not experience significant upregulation of the inflammatory or antioxidant gene transcripts examined; however, peripheral and placental parasitemia correlated positively with Il1β, Cox1, Cat, and Hmox1 placental transcript abundance." (PMID 35312688, 2022).
parasitemia (continued). "However, Il1β transcripts were positively correlated with both peripheral parasitemia at euthanasia (E15.5) and peripheral parasitemia AUC for mice infected on E6.5." (PMID 35312688, 2022). "On the other hand, the main factor associated with non-severe infections was the parasitemia values, that correlated only with perturbation of inflammatory markers, such as IL-4 and IL-1β, with a relatively lower number of symptoms." (PMID 34727121, 2021). "In addition to these inflammatory mediators, IL-1β mediates the control of intracellular parasite infections." (PMID 33061823, 2020). "In fact, in the later phases of infection, parasitemia and tissue parasitism were significantly reduced in 5-LO−/− mice and it is in accordance with previous studies showing that cytokines such as IL-1β, IL-6, IL-12, TNF-α, and IFN-γ play a relevant role in host killing mechanisms against T. cruzi." (PMID 25165415, 2014). "Levels of IL-8 only correlated with parasitemia in travelers, and IL-1β in immigrants." (PMID 23967342, 2013). "Furthermore, IL-10 and IL-6 positively correlated with parasitemia in immigrants and travelers, whereas IL-1β only correlated with parasitemia in immigrants, and IL-8 only in travelers." (PMID 23967342, 2013). "Participants with high parasitemia had raised TNF‐α (p < .001), IFN‐ɣ (p < .001), IL‐1β (p < .001), IL‐6 (p < .001), GM‐CSF (p < .001), and IL‐10 (p < .001), but reduced IL‐3 (p < .001) and TGF‐β (p < .001) than those with low parasitemia." (PMID 39240033, 2024). "There is a direct relation between the increase in parasitemia and the increase in the level of IFN-gamma and IL-1β gene elevation in infected equines in comparison with healthy non-infected control horses." (PMID 38967736, 2024). "Following infection, macrophages secrete inflammatory mediators such as IL-1β, IL-6, and TNF-α to control parasitemia." (PMID 36713380, 2022). "We assessed the serum levels of six cytokines (i.e. IL-1α, IL-1β, IFNγ, CXCL10, CXCL9, TNFα) at the first peak of parasitemia of both 1/148 and IL3000 infections." (PMID 35787830, 2022). "In parasites infection, NLRP12 can function in inflammasome formation and was crucial for caspase-1 activation and IL-1β production during rodent malaria infection." (PMID 34956178, 2021). "Although the cytokines (IL-1β, IL-4, IL-6, IL-12, TNF-α, and IFN-γ) were increased in all groups after the parasite infection, the cytokine levels of the group immunized with SAG1-VLPs were markedly reduced compared to the non-immunized infection group." (PMID 32325746, 2020). "IL-1β is a marker of NLRP3 inflammasome activation and essential for cell defense in response to parasite infection." (PMID 32891167, 2020). "Mice were infected with T. cruzi and mechanical hyperalgesia, thermal hyperalgesia, blood parasitemia, survival, and TNF-α and IL-1β levels were evaluated from 2 to 28 days p.i.." (PMID 33574810, 2020). "However, the role of Syk in IL-1β regulation during parasite infection is unknown." (PMID 31449558, 2019). "We demonstrated that parasite infection triggered NLRP3 inflammasome activation in the liver and increased the number of hepatic NLRP3+ and IL-1β+ macrophages in WT mice as observed in a viral hepatitis model." (PMID 29774028, 2018). "At the time of acute illness (day 1), subjects had upregulation of innate immune response, cytokine, and inflammation-related genes (IL-1β, IL-6, TNF, and IFN-γ), which was more frequent with parasitemias >100,000 per μL and body temperatures ≥39°C." (PMID 26491700, 2015). "Of interest, both IL-1β- and NLRP3 mice presented a slight but significant lower body temperature and parasitemia in the early phase of infection." (PMID 19696895, 2009). "Parasitemia was determined by the Brener method and relative gene expression (RGE) of six cytokines was evaluated by RT-qPCR to determine the Th1 response (IFN-γ, TNF-α, IL-1β, IL-12) and the Th2 response (IL-4 and IL-10)." (PMID 40743218, 2025).
parasitemia (continued). "Simultaneous pharmacological inhibition of caspase-8 and RIPK1 in primary monocytes reduces IL-1β release without affecting cell viability or parasite infection." (PMID 39548522, 2024). "In contrast, oocysts were absent from the baso (+) network, parasitemia was negatively correlated with plasma IL-3 and IL-1β, and gametocytemia was strongly positively correlated with plasma MIP-1β at 3 d p.i.." (PMID 35970557, 2022). "The production of pro-inflammatory cytokines (TNF-α, IL-1β, IL-6, and IFN-γ) in serum and brain homogenate of the vehicle-treated infected mice was significantly increased compared to the normal group on the peak day of parasitemia." (PMID 34975479, 2021). "Although WT parasite infection induces secretion of IL-1β compared with the uninfected BMDM, infection with Δmag1 parasites further doubles the secretion of IL-1β compared with WT parasites (P < 0.001; analysis of variance [ANOVA] with Tukey’s honestly significant difference [HSD] test)." (PMID 34006649, 2021). "Whereas IL-1β was strongly suppressed in PBMC from both uninfected and infected animals receiving BBE, the effect on other cytokines such as IL-6 appeared to be influenced by the parasitic infection, with the suppressive effect less evident in infected pigs." (PMID 35069576, 2021). "Furthermore, the immunization of SAG1-VLPs effectively decreased the production of specific cytokines, such as IL-1β, IL-6, TNF-α, and IFN-γ, after parasite infection." (PMID 32325746, 2020). "This improved control of parasite infection was dependent on the high production of IL-1β in macrophages lacking DC-SIGN." (PMID 29946317, 2018). "However, it remains unclear if IL-1β was responsible for controlling parasitemia, since the increase observed in the G[−] coinfected group may have been counterbalanced by a similar increase in IL-1Ra, as evidenced by similarities in the IL-1β : IL-1Ra ratio across the groups." (PMID 27418744, 2016). "The impaired production of IL-1β was not restricted to a system of human cell culture but was also observable when parasite infection preceded inflammasome activation in murine BMDMs." (PMID 26114647, 2015). "However, the secretion of IL-1β is not well documented, unlike other parasitic infections such as Toxoplasma gondii and Leishmania major." (PMID 40109888, 2025). "This elevation was directly correlated with the level of parasitemia in infected horses, marking the first study in Egypt to investigate T. equi cytokine parameters, specifically focusing on gene expression of IFN-gamma, TGF-β1, and IL-1β in naturally infected horses." (PMID 38967736, 2024). "In the current study, the pro-inflammatory cytokine IL-1β mRNA expression was significantly downregulated following primary and secondary infection with E. tenella when using UROEE and its chitosan-loaded nanoparticles as dietary prophylactic agents against E. tenella parasitic infection." (PMID 38492183, 2024). "Patients with detectable parasitemia measured by RT-PCR in peripheral blood had a higher concentration of TNF-α, IL-1β, IL-4, and IL-6, whereas those with negative RT-PCR showed elevated levels of IL-17A." (PMID 38133693, 2023). "Serum concentration of IL-1α, IL-1β, IFNγ, CXCL10, CXCL9, TNFα in non-infected mice and mice infected with either 1/148 or IL3000, at the first peak of parasitemia (Mean ± SEM; N=3–4)." (PMID 35787830, 2022). "Furthermore, the lack of IL-1β in caspase-1/11-deficient mice is accompanied by downregulated hepatic interleukin-17+CD8+ and interferon-γ (IFN-γ)+CD8+ T cells, implying that inflammasome-mediated IL-1β is involved in promoting liver adaptive immunity to control this parasitic infection." (PMID 30319645, 2018). "In these studies, IL-1β, IL-6, and TNF were upregulated more frequently in subjects with higher parasitemias and higher temperatures (data not shown)." (PMID 26491700, 2015).
parasitemia (continued). "Furthermore, a correlation was observed between parasitemia levels and the expression of immune response infection genes (IFN-gamma, TGF-β1, and IL-1β cytokines) in infected horses compared to non-infected equine." (PMID 38967736, 2024). "An animal study on dogs evaluating relationship of PCT with different inflammatory biomarkers (TNF-α, IL-1β, IL-6, and IFN-γ) produced during viral, bacterial, and parasitic infections showed that PCT showed a weak significant negative correlation with IFN-ꝩ levels in serum." (PMID 39343776, 2024). "The lack of IL-1β and TNF-α, both typically elevated in malarial disease, may also be due to downregulation by IL-10, which increases with rising parasitemia." (PMID 32958528, 2020).